CLXN (calaxin)
Description:
Component of the outer dynein arm-docking complex (ODA-DC) that mediates outer dynein arms (ODA) binding onto the doublet microtubule. Seems to regulate the assembly of both ODAs and their axonemal docking complex onto ciliary microtubules (By similarity). Regulates ciliary and flagellar motility and is required for cilia-driven determination of body laterality (By similarity).
Synonyms: EFCAB1; ODAD5; FLJ11767; CILD53
Tractability: Small molecule: a structure with a bound ligand is known.
Gene: Protein-coding gene on chromosome 8 (48,710,789 to 48,735,311, reverse strand). Ensembl gene ENSG00000034239.
Subcellular location: Cytoplasm, cytoskeleton, cilium axoneme; Cell projection, cilium; Cell projection, cilium, flagellum
Subcellular location (Human Protein Atlas): Mid piece; Principal piece; Nucleoplasm
Gene Ontology:
Molecular function: calcium ion binding
Biological process: cilium movement; flagellated sperm motility; outer dynein arm assembly; regulation of cilium movement; regulation of flagellated sperm motility; regulation of signal transduction
Cellular component: cilium; sperm flagellum; axoneme; motile cilium
Genetic constraint (gnomAD): Loss-of-function variants: 12 observed, 14.39 expected, observed/expected ratio (o/e) 0.83, 90% interval 0.53 to 1.35. The upper end of that interval is the gene's LOEUF score, 1.35, which puts it in group 5 of 6, group 1 being the genes least tolerant of losing a copy. Missense variants: 186 observed, 187.42 expected, observed/expected ratio (o/e) 0.99, 90% interval 0.88 to 1.12. Synonymous variants: 68 observed, 66.59 expected, observed/expected ratio (o/e) 1.02, 90% interval 0.84 to 1.25.
Gene-disease validity (ClinGen):
ClinGen rates the evidence that CLXN causes each of these diseases.
ciliary dyskinesia, primary, 53 (autosomal recessive): Strong.
Homologues: Orthologues: chimpanzee CLXN (99% identical), macaque CLXN (98% identical), rabbit CLXN (94% identical), mouse Clxn (92% identical), dog CLXN (91% identical), pig CLXN (90% identical), rat Clxn (82% identical), guinea pig CLXN (81% identical), tropical clawed frog clxn (68% identical), zebrafish clxn (63% identical), Caenorhabditis elegans ncs-7 (21% identical), Drosophila melanogaster CG5890 (19% identical), and 2 more. Paralogues in human: HPCA (28% identical), HPCAL1 (27% identical), NCALD (27% identical), KCNIP3 (26% identical), KCNIP4 (25% identical), HPCAL4 (25% identical), VSNL1 (25% identical), KCNIP2 (24% identical), NCS1 (24% identical), KCNIP1 (23% identical), GUCA1B (21% identical), RCVRN (21% identical), and 2 more.
Diseases named in the same sentence as CLXN in open-access papers:
CLXN is named in the same sentence as 8 diseases in open-access papers, as found by Europe PMC text mining. Sharing a sentence is not in itself a finding about the gene and the disease. The quoted sentences say what the papers report.
primary ciliary dyskinesia (3 papers, 2019 to 2025). A rare, genetically heterogeneous, primarily respiratory disorder characterized by chronic upper and lower respiratory tract disease. "Several of these functionally uncharacterized proteins are associated with human diseases including ciliary dyskinesia (CLXN), Lui-Jee-Baron syndrome (SPIN4), lymphoblastic leukemia (LNP1, SLX4IP), lethal skeletal dysplasia (TMEM263), and association to autism and fragile X syndrome (DIPK2B)." (PMID 40425816, 2025). "We have recently shown that Calaxin stabilizes outer arm dynein (OAD), and the knockout of Calaxin results in primary ciliary dyskinesia phenotypes in vertebrates." (PMID 38876797, 2024).
situs inversus (1 paper, 2019). A congenital condition in which there is complete right-to-left reversal of the position of the major thoracic and abdominal organs (that is, they are arranged in a mirror image of the normal positioning). "Here we show that the mice with a null mutation in Efcab1, which encodes calaxin, display typical phenotypes of primary ciliary dyskinesia, including hydrocephalus, situs inversus, and abnormal motility of trachea cilia and sperm flagella." (PMID 31240264, 2019). "Knockout of calaxin in zebrafish also causes situs inversus due to the irregular ciliary beating of Kupffer’s vesicle cilia, although the 9 + 2 axonemal structure appears to remain normal." (PMID 31240264, 2019).
CLXN also shares sentences with these, for which no sentence is quoted: Alzheimer disease (1 paper); autism (1); fragile X syndrome (1); Lethal skeletal dysplasia (1); Lui-Jee-Baron syndrome (1); lymphoblastic leukemia (1).